AKR7A2 (aldo-keto reductase family 7 member A2)
Description:
Catalyzes the NADPH-dependent reduction of succinic semialdehyde to gamma-hydroxybutyrate. May have an important role in producing the neuromodulator gamma-hydroxybutyrate (GHB). Has broad substrate specificity. Has NADPH-dependent aldehyde reductase activity towards 2-carboxybenzaldehyde, 2-nitrobenzaldehyde and pyridine-2-aldehyde (in vitro). Can reduce 1,2-naphthoquinone and 9,10-phenanthrenequinone (in vitro). Can reduce the dialdehyde protein-binding form of aflatoxin B1 (AFB1) to the non-binding AFB1 dialcohol. May be involved in protection of liver against the toxic and carcinogenic effects of AFB1, a potent hepatocarcinogen.
Synonyms: AFAR; AFAR1; AKR7; AFB1-AR1
Tractability: Small molecule: a structure with a bound ligand is known; it has a high-quality binding pocket. PROTAC: ubiquitination databases record sites on it; its protein half-life has been measured.
Target class: Enzyme; Oxidoreductase
Gene: Protein-coding gene on chromosome 1 (19,301,991 to 19,312,144, reverse strand). Ensembl gene ENSG00000053371.
Subcellular location: Mitochondrion; Golgi apparatus; Cytoplasm
Subcellular location (Human Protein Atlas): Cytosol; Golgi apparatus
Pathways (Reactome):
Metabolism: Aflatoxin activation and detoxification
Gene Ontology:
Molecular function: phenanthrene-9,10-epoxide hydrolase activity; protein binding; aldose reductase (NADPH) activity; electron transfer activity
Biological process: daunorubicin metabolic process; doxorubicin metabolic process; aflatoxin catabolic process; aldehyde metabolic process; carbohydrate metabolic process
Cellular component: cytosol; extracellular exosome; mitochondrion; cytoplasm; Golgi apparatus
Genetic constraint (gnomAD): Loss-of-function variants: 30 observed, 38.33 expected, observed/expected ratio (o/e) 0.78, 90% interval 0.58 to 1.06. The upper end of that interval is the gene's LOEUF score, 1.06, which puts it in group 4 of 6, group 1 being the genes least tolerant of losing a copy. Missense variants: 529 observed, 488.64 expected, observed/expected ratio (o/e) 1.08, 90% interval 1.01 to 1.16. Synonymous variants: 228 observed, 210.35 expected, observed/expected ratio (o/e) 1.08, 90% interval 0.97 to 1.21.
Homologues: Orthologues: chimpanzee AKR7A2 (99% identical), macaque AKR7A2 (73% identical), zebrafish akr1a1a (22% identical), Drosophila melanogaster CG6083 (21% identical), Caenorhabditis elegans C01G5.5 (19% identical), Caenorhabditis elegans C07D8.6 (19% identical), Caenorhabditis elegans Y39G8B.1 (18% identical), zebrafish zgc:56622 (18% identical), Caenorhabditis elegans F53F1.3 (17% identical), Caenorhabditis elegans Y39G8B.2 (17% identical), Caenorhabditis elegans F53F1.2 (16% identical), Drosophila melanogaster CG18547 (13% identical), and 4 more. Paralogues in human: AKR7L (82% identical), AKR7A3 (81% identical), AKR1A1 (25% identical), AKR1C2 (24% identical), AKR1C1 (24% identical), AKR1C3 (23% identical), AKR1D1 (23% identical), AKR1B10 (23% identical), KCNAB2 (23% identical), KCNAB1 (23% identical), AKR1C4 (22% identical), AKR1C8 (22% identical), and 4 more.
Diseases named in the same sentence as AKR7A2 in open-access papers:
AKR7A2 is named in the same sentence as 9 diseases in open-access papers, as found by Europe PMC text mining. Sharing a sentence is not in itself a finding about the gene and the disease. The quoted sentences say what the papers report.
melanoma (4 papers, 2020 to 2023). A malignant, usually aggressive tumor composed of atypical, neoplastic melanocytes. "In melanoma cells it has been demonstrated that in hypoxic conditions, EV exhibit a miRNome and proteome signature (AKR7A2, DDX39B, EIF3C, FARSA, PRMT5, VARS), which is associated with poor prognosis for the patients." (PMID 34439311, 2021). "Hypoxic melanoma EVs carried a hypoxic signature consisting of six proteins (AKR7A2, DDX39B, EIF3C, FARSA, PRMT5, VARS) which were significantly associated with a poor prognosis for melanoma patients." (PMID 32183388, 2020).
Alzheimer disease (2 papers, 2011). A progressive, neurodegenerative disease characterized by loss of function and death of nerve cells in several areas of the brain leading to loss of cognitive function such as memory and language. "AKR7A2 protein levels are elevated in the cerebral cortex of patients with Alzheimer disease." (PMID 22040021, 2011).
liver fibrosis (1 paper, 2024). "Based on the ceRNA network, lncRNA TNFRSF10A-DT/has-mir-873–5/RCC2, UBR4, and the AKR7A2 axis may construct a ceRNA network to participate in the progression of liver fibrosis." (PMID 38378545, 2024).
cancer (4 papers, 2013 to 2020). A tumor composed of atypical neoplastic, often pleomorphic cells that invade other tissues. "Of the 371 cancer-related genes detected in the TCGA dataset, 190 were significantly correlated with ALDH5A1 (130 positive/60 negative) and 178 with AKR7A2 (23 positive/155 negative)." (PMID 28032215, 2017).
tumor (4 papers, 2014 to 2025). "Furthermore, pathways involved in xenobiotic metabolism (GSTs, DHDH, AKR7A2, HSD11B1L, CYP1B1, UGTs), drug metabolism, nucleotide metabolism, and homologous recombination (RAD51) reflect the tumour’s ability to adapt to environmental stressors and resist therapy." (PMID 41007296, 2025). "No significant changes in expression of AKR1B1, AKR1D1, AKR7A2, CBR1, CYP2C8, and CYP2C9 between tumor and control tissues were found." (PMID 25526449, 2014).
AKR7A2 also shares sentences with these, for which no sentence is quoted: breast carcinoma (1 paper); cardiac hypertrophy (1); endometrial cancer (1); prostate carcinoma (1).